NTSR1 (neurotensin receptor 1)
Diseases named in the same sentence as NTSR1 in open-access papers (continued):
Sharing a sentence is not in itself a finding about the gene and the disease.
cancer (continued). "Another area of investigation is the use of NTSR1 overexpression in cancer cells as the target to deliver therapeutic molecules." (PMID 28316623, 2017). "Targeting of cancer cells which express NTSR1 ectopically is a useful strategy for both detection and therapy of NTSR1 expressing cancers." (PMID 28316623, 2017). "Previous evidence showed the potential use of the NTSR1 as a biomarker for cancer progression and as a component of personalized medicine in selective cancers, and this is consistent with our present result." (PMID 25657825, 2015). "We also successfully transformed these nanoparticles into actively targeted nanoparticles by functionalizing with anti-NTSR1-mAb to specifically target NTSR1-overexpressing cancer cells, hence able to avoid undesired accumulation in normal cells." (PMID 26410728, 2015). "Further, to make these nanoparticles more specific in their delivery of siRNA, we conjugated anti-NTSR1-mAb to the surface of these nanoparticles to target NTSR1-overexpressing cancer cells." (PMID 26410728, 2015). "In particular, NTSR1 activation induces cell proliferation, survival, migration and invasion through multiple oncogenic pathways in various cancers." (PMID 26298774, 2015). "It has reported that NTS and its high-affinity neurotensin receptor 1 (NTSR1) overexpress in several types of cancer and malignant cell lines." (PMID 25644759, 2015). "Transcriptional deregulation in the Wnt/beta-catenin pathway enhances or triggers NTSR1 expression in a great variety of cancer cells, including breast cancer." (PMID 24824754, 2014). "Neurotensin (NTS) receptor type 1 (NTSR1) displays unique structural and functional features to treat different cancers." (PMID 24824754, 2014). "The neurotensin (NTS)-polyplex consists of synthetic nanoparticles that can transfer plasmid DNA (pDNA) encoding any gene of interest into cells that express and internalize the NTSR1, including dopaminergic neurons and cancer cells." (PMID 24824754, 2014). "Exogenous activation of NTSR1 leads to cell proliferation, survival, mobility and invasion in cancer cells from diverse origin." (PMID 25249545, 2014). "The cascade of biological events from the interaction between NTS and NTSR1 to the activation of HERs receptor appears to be a major contributor to rapid cancer cell growth." (PMID 25249538, 2014). "Our findings implicate the NTS/NTSR1 complex as a contributor to cancer aggressiveness by enhancing concomitantly the expression and activation of three receptors EGFR, HER2, HER3." (PMID 25249545, 2014). "It has been reported that NTSR1 activation leads to cell proliferation, survival, mobility, and invasiveness in specific cancer cell types." (PMID 23285176, 2012). "Recently, the expression of NTSR1 was significantly correlated to an increase in the number of tumors when sporadic cancer was generated in mouse models by inflammation." (PMID 23335914, 2012). "The mechanisms involved in NTSR1 deregulation in cancer cells have been studied in the context of colorectal carcinogenesis." (PMID 23335914, 2012). "The implications of the previous sections suggest a more direct role for NTS/NTSR1 in cancer growth and progression, than has been previously attributed." (PMID 23335914, 2012). "NTSR-1 is overexpressed early during tumourigenesis in many cancers, suggesting that the neurotrophin signalling pathway plays a critical role in the development of cancer diagnosis and therapy." (PMID 39747850, 2025). "NTSR1 regulates EGFR transactivation in several cancer cells." (PMID 37508387, 2023). "Previous studies have demonstrated that the NTS/NTSR1 complex plays an essential role in regulating tumorigenesis, proliferation, apoptosis, metastasis, and differentiation in a variety of cancers, primarily through pathways such as Rho GTPases/FAK, IP3/DAG/Ca2+ release, and PKC/RAF-1/MAPKs." (PMID 37726723, 2023). "The roles of the NTS/NTSR1 complex have been characterized in cancer cells." (PMID 33034134, 2021).
cancer (continued). "The NTS/NTSR1 complex is an actor in cancer progression in human colonic adenomas and cancers." (PMID 31093954, 2019). "PD176252 (GRPR antagonist) and SR48692 (NTSR1 antagonist) inhibit cancer growth." (PMID 30008698, 2018). "Many anti-cancer drugs directed against NT and NTSR1 are currently being tested." (PMID 29467963, 2018). "Diverse expression levels of the NTSRs, especially increased expression of NTSR1, have been reported in various types of cancers (e.g., colon, pancreas, breast, lung and prostate); however, the molecular mechanisms for this altered expression pattern are not entirely known." (PMID 26298774, 2015). "Our array CGH results indicate that amplification of the NTSR1 locus may be one of the mechanisms by which NTSR1 methylation is reduced in cancer cells." (PMID 26334593, 2015). "Because NTSR1 functions as an oncogene and NTS-NTSR1 signaling is a potential target of anti-cancer therapy, methylation of NTSR1 could be a predictive biomarker of the responsiveness of CRC patients to such treatment." (PMID 26334593, 2015). "The NTS/NTSR1 complex could be used as a marker to identify subsets of human cancers, and thus make eligible new drugs, kinase inhibitors, or immunotherapy, targeting HERs protein or their downstream pathways." (PMID 25249545, 2014). "In this review, we elaborate on how the NTS/NTSR1 complex could be developed as a possible target for cancer therapy." (PMID 23335914, 2012). "There is emerging evidence that either NTS or NTSR1 can be utilized as a prognostic marker for various cancers due to aberrant expression noted in tumors and not detected in normal tissues, and that silencing of the genes can inhibit the tumorigenic activities in some cancer cells." (PMID 26298774, 2015). "Experiments using a specific antagonist or knockdown of the NTSR1 using short interfering RNA suggest that NTSR1 mediates the effects of neurotensin on cancer cells, although NTSR3/sortilin, which is often coexpressed in cancer cells, may modulate NTSR1 signalling." (PMID 21961726, 2011). "Neurotensin receptor 1 (NTS1) and Gastrin‐Releasing Peptide Receptor (GRPR) are both G‐protein coupled receptors with complementary profile of expression in several cancer types." (PMID 39908060, 2025). "Labeled ligands for the neurotensin receptor 1 (NTS1R), which is expressed in the CNS, the gastrointestinal tract,andin malignant tumors, are needed to investigate NTS1R-ligandbinding and NTS1R expression." (PMID 40899861, 2025). "Even though the three NTSR1 protein forms were detected in the endogenously expressing cancer cells, PANC1 and HT29, as well as in HEK293T-NTSR1 cells overexpressing the protein, the relative abundance of the three NTSR1 forms was not equivalent." (PMID 36949141, 2023). "Small-molecule modulators of neurotensin receptor 1 (NTSR1), a class A G-protein-coupled receptor (GPCR), has emerged as promising therapeutic agent for psychiatric disorders and cancer." (PMID 37514186, 2023). "NTSR1 regulates transactivation of HER2 and HER3 in NSCLC cells, leading to ERK and AKT activation, increasing cancer growth and survival." (PMID 37508387, 2023). "To assess the physiological relevance of our findings we treated HT29 and PANC1 cancer cells with Tunicamycin and PNGase-F which, as in HEK293T-NTSR1 cells, induced a strong increase of the NTSR1-LP form, while the NTSR1-high form was undetectable." (PMID 36949141, 2023). "The infiltration abundance of immune cells was analyzed by CIBERSORT, and the correlation heatmap in pan-cancer showed that MAP3K19 and NTSR1 were significantly correlated with immune infiltration in more types of tumors." (PMID 36439693, 2022). "Subsequently, further immune score, stromal score, and ESTIMATE score in the pan-cancer TME revealed the potential roles of MAP3K19 and NTSR1 in regulating stromal/immune scores and gene expression in tumors." (PMID 36439693, 2022).
cancer (continued). "There was significantly higher expression of NTS, NTSR1 and NTSR3 in cancer tissue compared to surrounding normal epithelium (median H-score 163.5 vs 97.3, p < 0.01)." (PMID 32764278, 2020). "Within the whole cancer tissue specimens, the distributions of NTS and NTSR3 were localised or diffuse, whereas NTSR1 was focal or patchy." (PMID 32764278, 2020). "There appeared to be significant positive correlations between the expression levels of NTS, NTSR1, and NTSR3 in normal surrounding epithelium and cancer tissue taken from the same individual." (PMID 32764278, 2020). "This study found significantly higher levels of expression of NTS, NTSR1, and NTSR3 in cancer tissue compared to surrounding normal epithelium from the same individual." (PMID 32764278, 2020). "NTSR1, NTSR2, GHSR, MLNR, and NMUR1 promoter hypermethylation presented discriminative ROC curve profiles, which clearly differentiate cancer tissues from normal tissues [Area Under Curve (AUC) = 0.6220, 0.5736, 0.8103, 0.6049, and 0.5631, respectively]." (PMID 31974445, 2020). "Whilst NTSR1 and NTSR3 are found in a series of human cancer cell lines, the role of NTSR2 is much less studied in CRC." (PMID 28316623, 2017). "Recent studies sustain that NTSR1 and NTS play a major role in cancer progression, malignancy, and metastasis because of the development of an autocrine loop." (PMID 24824754, 2014). "The NTS/NTSR1 complex has been proposed to contribute to cancer progression because of the various oncogenic effects induced by NTS in tumors and in cancer cells from diverse origins." (PMID 23335914, 2012). "The NTSR1 gene is a target of the Wnt/APC oncogenic pathways connected with the β-catenin/Tcf transcriptional complex, known to activate genes involved in cancer cell proliferation and transformation." (PMID 19156213, 2009). "However, we show that in contrast to cancer cells, which express more NTSR1-low, HEK293T cells overexpressing NTSR1 expressed more abundantly the NTSR1-high form." (PMID 36949141, 2023). "ESTIMATE analysis results of pan-cancer species analysis of MAP3K19 and NTSR1 in TCGA database." (PMID 36439693, 2022). "One of the most studied neuropeptides involved in cancer progression is neurotensin (NTS), the three known receptors of which (two G-protein coupled receptors, NTSR1 and NTSR2, and a type I receptor, NTSR3) are expressed in numerous cancers and particularly in digestive cancers." (PMID 36233189, 2022). "Despite this, the findings corroborated that there was almost no NTSR1 protein expression in normal epithelium and higher expression in cancer tissue." (PMID 32764278, 2020). "Similarly, there was significantly higher expression of NTSR1 and NTSR3 in cancer tissue compared to corresponding normal epithelium (p < 0.01, Related-Samples Wilcoxon signed rank test)." (PMID 32764278, 2020). "NTSR1 positivity was observed in cancer epithelium but was negative or very weakly positive in normal epithelium." (PMID 32764278, 2020). "Incidentally, so far it has been shown that only N-glycosylated isoforms of Neurotensin receptor-1 (NTSR-1), a GPCR that has been identified as a mediator of cancer progression, are able to localize with membrane structured microdomains by palmitoylation for efficient mitogenic signaling." (PMID 30979007, 2019). "Through NTSR1, NTS signaling mediates cancer cell proliferation, survival, migration and invasiveness by activating a variety of signaling molecules, including protein kinase C (PKC), extracellular signal-regulated kinase 1 and 2 (ERK1/2) and interleukin (IL)-8." (PMID 26334593, 2015). "However, the mechanisms for the expression of NTSR1 in cancer tissues including NETs, have not been well-defined." (PMID 26298774, 2015).
adenocarcinoma (7 papers, 2012 to 2020). A common cancer characterized by the presence of malignant glandular cells. "We previously found that NTSR1 expression is associated with adenocarcinomas prognosis." (PMID 25249545, 2014). "NTSR1 expression in adenocarcinoma is correlated with diffuse cytoplasmic or nuclear β-catenin localization." (PMID 33268796, 2020). "In a clinical series of 138 stage I primary NSCLC adenocarcinomas treated only with surgery, NT was expressed in 60.4% of the cases, NTSR1 was expressed in 59.7% and both, NT and NTSR1, were expressed in 38.8% of the cases." (PMID 32336282, 2020). "The proportion of NTSR1-positive epithelial cells progressively increased in biopsies taken from colonic epithelium with inflammation, dysplasia, and adenocarcinoma in the context of inflammatory bowel disease." (PMID 32764278, 2020). "Multivariate analysis in all adenocarcinoma patients showed that pN (p=0.0000001), pT (p=0.00004) and NTSR1 score 2 (p=0.0069) were independent predictors of worse survival." (PMID 25249545, 2014). "NTSR1 mRNA expression studied by in situ hybridization showed a higher level of expression in adenocarcinoma as compared to adenomas." (PMID 23335914, 2012). "The study by immunoprecipitation using the adenocarcinoma cell line HT29, demonstrated that the NTSR3 forms heterodimers with the NTSR1." (PMID 23335914, 2012). "In non-small lung cancer cells, NTS and NTSR1 expression were not detectable, whereas 60% of patients with stage 1 adenocarcinoma expressed either NTS or NTSR1 and 40% expressed both markers." (PMID 23335914, 2012).
breast (2 papers, 2014 to 2015). "NTSR1 is a target of the Tcf/β-catenin complex in the Wnt signaling pathway, and activation of NTSR1 expression is an early event in colorectal tumorigenesis." (PMID 26334593, 2015).
cardiovascular disease (2 papers, 2014 to 2021). "Apelin/APJ and NT/NTSR1 system are co-expressed in a wide range of tissues, playing a role in neuroprotection and involved in neuropsychiatric and cardiovascular disease 20,21." (PMID 25164432, 2014). "These novel data provide evidence for a physiological role of APJ/NTSR1 heterodimers in terms of ERK1/2 activation and increased intracellular calcium and induced cell proliferation and provide potential new pharmaceutical targets for cardiovascular disease." (PMID 25164432, 2014).
NTSR1 also shares sentences with these, for which no sentence is quoted: ovarian carcinoma (3 papers); endometrial carcinoma (2); head and neck squamous cell carcinoma (2); autism (1); behavioral disorders (1); benign prostatic hyperplasia (1); brain cancer (1); brain glioma (1); colonic adenomas (1); dysplasia (1); essential hypertension (1); Insulin resistance (1); invasive breast carcinoma (1); invasive carcinoma (1); ischemia (1); large bowel adenocarcinomas (1); leukemia (1); lung squamous cell carcinoma (1); lymphoma (1); mesothelioma (1); myeloma (1); Parkinson disease (1); phobia (1); psychiatric disorder (1); sarcoma (1); Sezary syndrome (1); small cell lung carcinoma (1); Stroke (1); substance abuse (1).